CD4 (CD4 molecule)
Diseases named in the same sentence as CD4 in open-access papers (continued):
Sharing a sentence is not in itself a finding about the gene and the disease.
AIDS (continued). "First, the prognostic strength of the GRGs for rates of disease progression should be comparable to that of the CD4+ cell count and plasma HIV viral load, contemporary laboratory markers used to assess AIDS prognosis in HIV-positive patients." (PMID 18776933, 2008). "This revealed that individuals whose CD4+and CD8+ Gag-specific T-cell response were in the highest tertile had a tendency for prolonged AIDS-free survival." (PMID 18648514, 2008). "CD4 T-cell count and HIV RNA level (viral load) are the most widely used markers of progression to AIDS and death in HIV-1 infected persons." (PMID 17888148, 2007). "CD4+ T cell counts and HIV-1 RNA levels were measured multiple times during the follow-up period for the AIDS Link to the Intravenous Experience (ALIVE) SC participants." (PMID 17257057, 2007). "In reconsidering the setpoint theory for HIV RNA, we analyzed the evolution of CD4 T-cell count and HIV-1 RNA level from HIV seroconversion to AIDS diagnosis." (PMID 17888148, 2007). "We analyzed sequential CD4 and CD8 numbers, percentages and ratios in 218 of our HIV infected patients to determine the most reliable predictor of an AIDS-related event." (PMID 16916461, 2006). "In HIV/AIDS patients, the vast majority of the HIV infection is confined to the CD4+ subset of T cells in lymphoid tissues and the CD4 molecule was identified more than twenty years ago as the primary receptor for HIV infection." (PMID 16600047, 2006). "Hazard ratios of CD4 cell count, plasma HIV RNA level and the use of antiretroviral therapy in the second quarter of 1997 for progression to AIDS or death after 1997." (PMID 16710078, 2006). "Hazard ratios of combination of CD4 cell count, plasma HIV RNA level and the use of antiretroviral therapy in the second quarter of 1997 for progression to AIDS or death after 1997." (PMID 16710078, 2006). "In fact, higher frequency of patients with AIDS at HIV diagnosis, lower T CD4+ cell count and higher mortality in older subjects in respect of younger were observed." (PMID 15530169, 2004). "Low CD4 cell counts and high viral load at the time of HIV diagnosis were associated with both AIDS and non-AIDS mortality without a significant difference." (PMID 41597637, 2026). "AIDS, acquired immunodeficiency syndrome; ALHIV, adolescents living with HIV; ART, antiretroviral therapy; CD4, cluster of differentiation; COREQ, consolidated criteria for reporting qualitative research; HCP, healthcare provider; HIV, human immunodeficiency virus; SD, standard deviation." (PMID 41190626, 2025). "We explored CD4 measurement (proportion of PWH with a CD4 result available) and prevalence of CD4 <200 cells/μL (hereafter “CD4 <200”) at ART initiation within the International epidemiology Databases to Evaluate AIDS (IeDEA) global collaboration." (PMID 39501773, 2025). "All 3 persons presented with no HIV- or AIDS-defining conditions or other symptoms and a median CD4+ T-cell count of 690 cells/mm3 (IQR, 650–730)." (PMID 40599486, 2025). "However, due to her most recent CD4 levels, it is evident that the patient had not been compliant with darunavir/cobicistat/emtricitabine/tenofovir alafenamide, enabling her infection to progress further into AIDS, deteriorating her immune system, and potentially causing new mutations." (PMID 41246707, 2025). "Normalization of the CD4/CD8 ratio to more than 1 is considered an important measure of immunological response to ART, and a low CD4/CD8 ratio is a prognostic marker for both opportunistic infections and non-AIDS morbidity and mortality." (PMID 40738892, 2025). "PLHIV with low CD4 + T cell counts or an AIDS-defining event, regardless of their CD4 + T cell count at diagnosis, are classified as late presenters." (PMID 40098016, 2025). "The median (IQR) CD4 T-lymphocyte percentage was 15% (6%–25%) in PWH with AIDS and 22% (12%–29%) in PWH without AIDS." (PMID 39067055, 2025).
AIDS (continued). "Conversely, the negative correlation of Mucor with CD4 counts highlights its potential role in opportunistic infections during advanced AIDS stages." (PMID 40415955, 2025). "The blood tests revealed AIDS (HIV—1 viral load, 2,750,000 copies/mL; CD4+ T cell count—53 cells/mm3; and CD8+ T cell count—517 cell/mm3) and latent syphilis (VDRL-positive and TPHA-positive, without chancre or other clinical symptoms to suggest acute infection)." (PMID 40871318, 2025). "He had a recent diagnosis of AIDS, with no prior CD4+ T-cell count monitoring or antiretroviral therapy (ART)." (PMID 40980170, 2025). "We also analyzed whether known risk factors for being an INR (male sex, older age, a low CD4 count, a low CD4:CD8 ratio at diagnosis, and the AIDS stage) were different between subtype subgroups, which could influence the results." (PMID 40003876, 2025). "The median CD4+ lymphocyte count nadir was 448.5 [IQR: 229–641] cell/mm3 in MLHIVs with no history of AIDS-defining events and 96.5 [IQR: 12–328] in those with a history of at least one AIDS-defining event." (PMID 41150371, 2025). "Advanced HIV disease POCT (CD4, LAM, CrAg) was scarcely mentioned in the national HIV/AIDS strategic plans, except in Zimbabwe’s 2022 operational manual, which mentions that AHD POCT should also be performed in the community by trained cadres (nurses, primary counsellors and microscopists)." (PMID 41460810, 2025). "LP is defined as persons presenting for care with a cluster of differentiation 4 (CD4) count below 350 cells/μL or presenting with an acquired immunodeficiency syndrome (AIDS) defining event, regardless of the CD4 cell count." (PMID 40191382, 2025). "By using CEM-CD4+ T cells, a kind of leukocyte cell line, Murray and his colleagues successfully detected and enumerated the CD4+ T lymphocyte subset, which helps identify people with severe HIV disease/AIDS." (PMID 39852084, 2025). "All animals had signs of immunosuppression including depleted peripheral CD4 counts (<500 cells/μL of blood) in 4/7 (57%) of animals (median 494 (274-1090) cells/μL of blood) and a blood CD4/CD8 ratio of <1, a biomarker of HIV/AIDS disease progression, in 7/7 (100%) of animals." (PMID 40463375, 2025). "CD4 + T cell counts revealed that 26 out of 54 individuals (26/54) in the Acute-ART group had counts above 500 cells/μL, compared to 14 out of 36 individuals (14/36) in the AIDS-ART group." (PMID 39788938, 2025). "Patients with advanced HIV/AIDS, especially those with CD4 counts <50 cells/μL and who are not on effective antiretroviral therapy (ART), are at the highest risk for severe CMV GI disease." (PMID 41262801, 2025). "This situation was not applicable in this case as the patient did not have any signs and symptoms of AIDS, and her CD4 count was normal." (PMID 41246379, 2025). "Late presenter (LP) to HIV care is defined as the one who is either presenting with a CD4 count below 350 cells/mm3 or presenting with an AIDS-defining illness, regardless of the CD4 count." (PMID 40390714, 2025). "Participants with CD4+ T-lymphocyte counts > 350 cells mm−3, or without AIDS-related symptoms, displayed significantly better scores in multiple domains (p < 0.05)." (PMID 41415224, 2025). "Notably, NFAT5 acts as a host factor-viral enhancer for HIV-1 subtype viruses in HeLa CD4+ cells and THP-1 monocytes, suggesting that disrupting this interaction could inhibit viral replication and potentially slow acquired immunodeficiency syndrome (AIDS) progression." (PMID 40421201, 2025). "A 30-year-old woman with advanced AIDS (CD4 14 cells/μL, non-adherent to antiretroviral therapy) presented with three weeks of jaundice, fatigue, and fever." (PMID 40843879, 2025). "This is most commonly observed in patients with AIDS and CD4 counts below 50 cells/μL who are not receiving antiretroviral therapy (ART)." (PMID 41262801, 2025).
AIDS (continued). "A Canadian study showed a significant association between missed opportunities and AIDS diagnosis within three months of HIV diagnosis but did not distinguish between CD4 counts below 200 cells/mm3 and AIDS-defining conditions." (PMID 39204283, 2024). "Measures of the success rate of ART include successful viral load suppression (<50 copies/mL), an increase in CD4+ count (>200 cells/μL), and the absence of AIDS-defining conditions after ART." (PMID 39398487, 2024). "Risk factors for AIDS-related mortality include age ≥40 years, PWID, heterosexual men, women infected through sex, history of AIDS-defining illnesses, CD4 <200 cells/μL at cohort entry, ≥2 comorbidities, and nonreceipt of ART." (PMID 38560603, 2024). "We found that PLWH with KS were younger than HIV-negative participants with cKS while exhibiting similar clinical presentations, and a lower CD4/CD8 ratio as a surrogate marker of chronic inflammation and risks of non-AIDS comorbidities, in line with previous findings." (PMID 39100526, 2024). "Therefore, several models have been proposed to characterize the delay in HIV diagnosis, and most of these agreed on the reliability of CD4 count in defining the late presentation, notably the concurrent diagnosis of HIV and AIDS." (PMID 38398466, 2024). "Nonwhite ethnicity, history of AIDS, recent HIV diagnosis, absence of ART,CD4+ T cell counts of < 200 cells/mm3, detectable HIV viral load,having at least one comorbidity (not related to HIV/AIDS), and ≥ 4 COVID-19 symptomsincreased the risk of a severe case." (PMID 39536214, 2024). "Advanced disease is defined as having a CD4 count below 200 cells/μL or the presence of an AIDS-defining illness, regardless of the CD4 count." (PMID 38594292, 2024). "These trends in the number of new HIV and AIDS diagnoses and in the proportion of advanced diagnoses (CD4 <350 cells/mmc—data not shown) were confirmed at regional level with a powerful sample size, although with shortened follow‐up duration." (PMID 39513741, 2024). "Two negative patients had AIDS-associated PML and were among the AIDS patients with the lowest CD4 T cell counts and CD4/CD8 ratios." (PMID 39086476, 2024). "Even with suppression of detectable plasma HIV virus and CD4+ T cell recovery, PWH have higher age-adjusted mortality and increased rates of serious non-AIDS adverse events, including malignancies and cardiovascular disease (CVD), compared with age-matched cohorts without HIV." (PMID 38564303, 2024). "The oral intake of other probiotic strains (i.e., L. rhamnosus GR-1, GG, and HN001) for at least 30 days has been shown to alleviate diarrhea and delay the decline of CD4+ lymphocytes and morbidity in HIV/AIDS subjects by improving mucosal immune response and enhancing effects of antivirals." (PMID 39273118, 2024). "Predictors for AIDS-related mortality included being aged ≥40 years, not being a man who have sex with men, history of AIDS-defining illnesses, CD4 < 200 cells/μL, ≥2 comorbidities, and nonreceipt of ART." (PMID 38560603, 2024). "The European Late Presenter Consensus working group has established a definition of late presenters as persons presenting for care with a CD4 count below 350 cells/μL or those who present with an AIDS-defining event, regardless of their CD4 count." (PMID 39037975, 2024). "The value of CD4 count is necessary for the calculation of delay time, and those with initial HIV diagnosis being AIDS but having no CD4 counts within three months of initial diagnosis were excluded." (PMID 38896338, 2024). "Since early ART initiation has been shown to reduce levels of T cell activation, we hypothesized that it might also accelerate the rate of CD4/CD8 ratio normalization and avoid the development of non-AIDS events." (PMID 38324873, 2024).
AIDS (continued). "According to the Jointed United Nations Programme on HIV/AIDS (UNAIDS) 2021 Report, in Latin America, the percentage of patients with a CD4 cell count of <200 cells/mm3 at diagnosis varies from 10% in Uruguay to 44% in Paraguay, with Brazil recording 27% of cases." (PMID 38482527, 2024). "Non-AIDS mortality increased with age, injection drug use, heterosexual men, socioeconomic deprivation, CD4 200 to 349 cells/μL, nonreceipt of ART, and comorbidities, but migrants had lower risk (adjusted hazard risk, 0.69 [95% CI.57–.83])." (PMID 38560603, 2024). "The maximum frequency of CD4+ T cells expressing IL-4 was seen in HIV-infected individuals without AIDS, whereas the rate of IL-10-producing CD4+ T cells was highest in patients with AIDS." (PMID 39062756, 2024). "For raising CD4+ and CD8+, recombinant IL-7 and immune checkpoint inhibitors for relapsing VL might be conducted for patients with relapsing VL and AIDS." (PMID 38921748, 2024). "However, published studies included fewer patients with a nadir CD4+ count below 200 cells/μL, and the impact of CH in HIV cohorts with prior AIDS and/or IRIS remains unexplored." (PMID 38564303, 2024). "This population has been poorly studied and has not been considered as a target population for multiple interventions since they are unlikely to progress to AIDS, they have significantly increased their CD4+ T cell counts and immune responses." (PMID 39351495, 2024). "Late diagnosis is defined as an HIV diagnosis with a CD4+ T-cell count below 350 cells/μL or an AIDS-defining event; cases diagnosed during the acute stage are not classified as late, even when the individual has a low CD4+ T-cell count." (PMID 39611209, 2024). "A critical factor in this scenario was the late diagnosis of HIV, defined as presenting for care with a CD4 count below 350 cells/mL or with an AIDS-defining event, irrespective of CD4 count, excluding acute infections." (PMID 39749085, 2024). "Multiple studies have consistently demonstrated a significant correlation between baseline CD4+ T cell count and HIV/AIDS-related mortality, revealing that individuals with lower baseline CD4+ T cell counts tend to have a higher risk of death and worse prognosis." (PMID 38454987, 2024). "This expansion of viral RNA in plasma was associated with a remarkable increase in extrafollicular SIV-infected PD-1 CD4+ T cells, a pattern seen in chronic-phase viremic SIVmac239-infected RMs that progress to AIDS rapidly, but not in elite controller RMs." (PMID 38557496, 2024). "We used these data to assess the relative odds of having an AIDS-defining event (ADE) within 1 year of ART initiation (Y) between patients who were/were not ART-naive at enrollment (X), while adjusting for square-root-transformed CD4 at ART initiation (Z)." (PMID 39629097, 2024). "The European Late Presenter Consensus working group defines late presentation as a diagnosis of HIV with a CD4 count ≤ 350 cell/μL or the occurrence of an AIDS-defining event, regardless of the CD4 cell count." (PMID 39064161, 2024). "Similarly, in Malaysia, according to the Country Progress Report on Global AIDS Monitoring 2022, HIV late presenters were defined as individuals with a CD4 count less than 350 cells/mm3." (PMID 39037975, 2024). "Non-AIDS mortality risk rises with age ≥30 years, PWID, heterosexual men, socioeconomic deprivation, HIV diagnosis in 2015 through 2020, CD4 200 to 349 cells/μL, nonreceipt of ART, and ≥1 comorbidity." (PMID 38560603, 2024). "This was underscored by the discovery of rare HIV-infected patients who did not progress to AIDS and maintained significant numbers of CD4+ T cells for many years after infection." (PMID 38557723, 2024). "We defined late presentation as having a CD4 count < 350 or AIDS-defining event regardless of CD4 count." (PMID 38594292, 2024).
AIDS (continued). "In line with national guidelines at the time, maternal ART was discontinued after weaning for participants with CD4+ T cell counts of >200 cells/mm3 and no AIDS-defining illness." (PMID 37112830, 2023). "AIDS patient is defined as a person presenting with a CD4 count < 200 cells/μL or presenting with an AIDS-defining event, regardless of the CD4 cell count." (PMID 36895684, 2023). "Late HIV diagnosis, defined as CD4 count < 350 cells/μL or AIDS at diagnosis regardless of CD4 count, still represents an unmet need, with half of PWH being diagnosed late." (PMID 37415770, 2023). "Initiatives have moved towards a harmonised definition, with the consensus definition of late presentation being defined as a CD4 cell count below 350 cells/mm3 at the time of HIV diagnosis or presenting with an AIDS-defining event regardless of CD4 count." (PMID 37351535, 2023). "Testing and treating all HIV patients without having to wait for the reduction in their CD4 count entails having adequate resources for basic HIV/AIDS testing and treatment supplies." (PMID 37173757, 2023). "Early ARTs were developed based on the observed low count of CD4+ T-Cells in clinical symptoms of AIDS as compared to the most recent ones that are administered immediately after a patient is diagnosed regardless of the level of CD4+ cells." (PMID 37632074, 2023). "The CD4/CD8 ratio tends to present greater stability over time than the absolute counts of CD4 and CD8 cells, and its predictive value for events unrelated to AIDS has been described as exceeding that of the absolute CD8 count in individuals with restored CD4 counts (> 500 cells/μL)." (PMID 36627565, 2023). "Indeed, a large proportion of DP individuals (10/15, 66.67%) had <200 CD4+ T cells/μL at the time of HIV-1 diagnosis, which is considered AIDS-defining." (PMID 37601355, 2023). "Throughout the follow-up, no significant gut dysfunction was observed in the CD4+-cell-depleted AGMs, none of which progressed towards AIDS, nor developed opportunistic infections." (PMID 36813761, 2023). "Combination antiretroviral therapy has demonstrated proved effectiveness in suppressing viral replication and significantly recovering CD4+ T cell count in HIV type-1 (HIV-1)-infected patients, contributing to a dramatic reduction in AIDS morbidity and mortality." (PMID 37608956, 2023). "In summary, the results of this large prospective cohort support the use of a CD4/CD8 ratio cut-off of <0.3, regardless of CD4 count, to identify PWH with an excess risk of cardiovascular events, non-AIDS-defining malignancies, and all-cause mortality." (PMID 37639938, 2023). "Despite efforts to increase testing and care across Asia, an estimated 34–72% of people do not present for care until their CD4 cell count has decreased below 350 cells/mm3 or present with an AIDS-defining event." (PMID 37351535, 2023). "Suboptimal immune recovery has been clinically related to some factors such as aging, increased innate and adaptive immune activation and immunosenescence phenotype, low nadir CD4+ count below 200 cells/mm3, low CD4/CD8 ratio, AIDS, and poor baseline clinical status, among others." (PMID 36769822, 2023). "However, the frequencies of HLA-ABClow in p24+ cells inversely correlated with the CD4 count, highlighting a lower HLA-ABC downregulation when CD4 is low, in other words, during AIDS." (PMID 38420260, 2023). "CD4+-cell-depleted AGMs maintain gut integrity, control immune activation and do not progress to AIDS." (PMID 36813761, 2023). "Late HIV diagnosis is characterized by an individual being diagnosed with HIV for the first time with a CD4 count < 350 cells/μL or due to an AIDS-defining event, irrespective of the CD4 cell count." (PMID 37896874, 2023). "Additionally, the same correlations have been observed for Ki67+ in CD4+ T cells, while immune activation (HLA-DR+, CD38+) in CD4+ T cells has been detected as highest in AIDS individuals." (PMID 38420260, 2023).